STAT3 (signal transducer and activator of transcription 3)
Diseases named in the same sentence as STAT3 in open-access papers (continued):
Sharing a sentence is not in itself a finding about the gene and the disease.
tumor (continued). "Furthermore, we reveal an inhibitory role for STAT3 and IL-10 in CD103+ cDC1 vaccine efficacy, as assessed by tumor growth and mouse survival." (PMID 31947933, 2020). "The authors indicated that pimozide inhibited STAT3 and STAT5, regulating tumor immunity." (PMID 33489912, 2020). "Therefore, either STAT3 could generate paracrine signals capable of inhibiting NFκB activation; or tumors could inhibit NFκB, through other mechanisms that do not directly involve STAT3, but that were reduced as treatment with STAT3 inhibition reduced tumor growth." (PMID 33330068, 2020). "In light of the important role of STAT3 in tumor development and progression in several types of cancer, we wondered whether α-MGT could inhibit the growth of other tumor cells harboring constitutive activation of STAT3." (PMID 31980595, 2020). "In addition, α-MGT also suppressed the activation of STAT3 induced by IL-6 or EGF, two major growth factors of tumour cells that activate STAT327." (PMID 31980595, 2020). "In one study carried out to assess the function of STAT3 on CD8+ T cells, it was seen that removal of STAT3 results in an increased expression of CXCL10 receptor (CXCR3), which increases an accumulation of T-cells at the tumor site." (PMID 33291616, 2020). "Using the ratio of p-STAT3 expression in tumor/adjacent liver tissues as the cut-off value, HCCs with higher p-STAT3 expression in HCC tissues were classified into High p-STAT3 group and others were Low p-STAT3 group." (PMID 31942180, 2020). "The effect of RBP4 on tumor tissue and cancer cells in this model is not dependent on STAT3 phosphorylation." (PMID 32156052, 2020). "This review summarises the functions of STAT3 and STAT5 in the regulation of some metabolism-related genes and the importance of oxygen in the tumour microenvironment to regulate cell metabolism, particularly in the metabolic pathways that are involved in energy production in cancer cells." (PMID 31947710, 2020). "The results suggested that STAT3 expression level was inversely correlated with tumor purity, indicating that STAT3 was highly correlated with non-tumor cells, especially in BLCA (r = −0.383), KICH (r = −0.436), and LIHC (r = −0.315)." (PMID 32486001, 2020). "A Phase II trial of ruxolitinib in triple-negative breast cancer confirmed inhibition of STAT3 activation in patient tumor samples; however, no clinical response was observed, as evaluated by the RECIST criteria, and the study was terminated (NCT01562873)." (PMID 33521321, 2020). "It has been reported in the literature that AKT and STAT3 have also been identified to be involved in the regulation of downstream factors, including PCNA, Bcl2 and CyclinD1, and to manage tumor proliferation and apoptosis." (PMID 32463472, 2020). "Several studies demonstrated that Src, a proto-oncogenic nonreceptor tyrosine kinase, activated STAT3, which resulted in the stimulation of tumor growth and the pathway plays important roles in tumorigenicity 11-13." (PMID 31929760, 2020). "IL-6/STAT3-dependent Oct4 expression has also been observed in HCC cell lines and tumor homografts." (PMID 33343368, 2020). "Similarly to miR-146a, miR-155 upregulation promotes cell proliferation, colony formation, and xenograft tumor growth in BC models by negative regulation of SOCS1 and SHIP1, leading to constitutive STAT3 activation and pro-tumor inflammation." (PMID 32793185, 2020). "Moreover, it is accepted that the phosphorylation of STAT3 is involved in EMT and tumour metastasis." (PMID 32285603, 2020). "The adipokine IL-6 is able to promote tumour growth and metastasis, while EGCG was able to inhibit IL-6 induced VEGF expression and angiogenesis in both in vitro and in vivo models of gastric cancer by suppressing STAT3 activity." (PMID 32731620, 2020).
tumor (continued). "Additionally, OPN as a tumor biomarker is induced through the TM4SF4/GSK3β/β-catenin axis, JAK2/STAT3, and FAK/STAT3 signaling, and is additionally regulated via formation of positive feedback autocrine loop that results in cells acquiring CSC-like properties." (PMID 31952344, 2020). "Thus, STAT3 inhibition via CBD increases the Th1 immune response and is a major source of ROS production, leading to tumor cell death." (PMID 33143283, 2020). "Collectively, NaB could reduce tumor burden and inhibit JAK2/STAT3 signaling axis activation in mouse xenograft tumor models." (PMID 32518521, 2020). "Therefore, miR-125b plays a tumor suppressor role, targeting both MMP13 and STAT3 mRNAs with inhibition of cell proliferation and migration, and induction of cell apoptosis." (PMID 32911687, 2020). "As for precedence of non-canonical signaling within the JAK-STAT pathway, STAT3 has been reported as a non-canonical activator of the NF- κB pathway to promote myeloid-derived suppressor cells in the tumor microenvironment." (PMID 32450888, 2020). "Thus, taken together, our results suggest STAT3 and IL-10R signaling in CD103+ cDC1s inhibits their ability to induce systemic anti-tumor adaptive immunity." (PMID 31947933, 2020). "Besides, when tumor cell lines were treated with 40 μM ACT001, both PD-L1 and p-STAT3 proteins were hardly detected by IF staining." (PMID 32483429, 2020). "In addition, napabucasin, an inhibitor of STAT3 signaling, able to decrease number of ALDH positive cells and sensitize tumor cells to cisplatin, in combination with cisplatin was investigated." (PMID 32774158, 2020). "In summary, our findings have revealed the link between IL-6/STAT3 pathway and CD73-adenosine axis, which might play an important role in tumor growth and chemoresistance in NPC." (PMID 32127934, 2020). "Moreover, NF-κB, STAT3 and PI3K signaling together play a critical role in cell resistance and survival in B-cells and neoplasms." (PMID 33081347, 2020). "HPSE also bypasses the tumour-suppressive roles of several genes, such as PTEN, STAT3 and TGF-β." (PMID 33256730, 2020). "Interestingly, tumor infiltrating NK cells upon engagement with 4-1BBL expressing tumors upregulate surface CD73 expression and acquire immunosuppressive properties via STAT3 resulting in IL-10 and TGF-β production." (PMID 33371456, 2020). "Despite the fact that UTMC-based STAT3 decoy delivery inhibited tumor growth, complete regression of tumor was not achieved and tumor growth recommenced after the treatment was terminated (Day 7)." (PMID 33206698, 2020). "The cytokines produced in response to increased ROS levels—e.g., IL-1β, IL-6, and TNF-α—activate the signaling through the NF-κB and signal transducer and activator of transcription 3 (STAT3) pathways, which have been demonstrated to participate in tumor progression." (PMID 32604771, 2020). "Some studies also showed that SPP1 contributed to tumor cell migration, invasion and survival through PI3K-Akt and STAT3 signaling, and could also promote tumor growth and metastasis by inducing angiogenesis." (PMID 33240930, 2020). "Therefore, RCC2 plays a vital role in tumor proliferation, tumorigenicity, and promotes radioresistance by activating transcription of DNA methyltransferase 1 (DNMT1) through a p-STAT3 dependent pathway." (PMID 33521058, 2020). "Similarly, another study also found that NC reduced tumor volume and tumor weight in mice via suppression of ERK, STAT3, and SHH pathways, and regulation of Bcl-2, Bax, CyclinD1, VEGF pathway." (PMID 31956371, 2020). "Even though NO has been described to induce the senescence of tumor cells, it also mainly modulates the expression of SASP factors, as well as other senomorphic agents, by regulating numerous signaling pathways such as NF-κB and STAT3." (PMID 32370259, 2020). "Despite its critical role in tumor cell proliferation and survival, the posttranscriptional fate of STAT3 has not been thoroughly defined." (PMID 32483468, 2020).
tumor (continued). "We have found that STAT3 possesses a noncanonical function, is capable of associating with HP1, promoting heterochromatin formation, and suppressing tumor progression." (PMID 32087696, 2020). "DC differentiation can be completely restored using repressing approaches based on STAT3 inhibition, which abrogated the negative effects of tumor-derived factors on myeloid-cell differentiation." (PMID 33584695, 2020). "Consistent with the findings in tumor, HSPH1 was required for STAT3 phosphorylation in LPS-AMs." (PMID 32091104, 2020). "Mechanistically, a lot of tumor- and TME-derived signals, such as hypoxia, EGFR-induced STAT3 and NF-κB activation, might be responsible for upregulated NEAT1 expression." (PMID 32843056, 2020). "In our previous report, we used a nuclease-resistant internalizing RNA aptamer, named Gint4.T, to bind and inhibit the platelet-derived growth factor β receptor (PDGFRβ), and then designed an AsiC (Gint4.T-STAT3) for the delivery of a STAT3 siRNA to GBM cells, inhibiting tumour cell growth." (PMID 32486489, 2020). "Besides, the maximum sample size of tumor patients was 12 in the HPA dataset, which made the protein expression of STAT3 in cancer less objective and needed further investigation and verification." (PMID 32486001, 2020). "Since the HP1-binding motif PxVxI is conserved in all STAT proteins including STAT3, we sought to investigate whether uSTAT3 can also bind HP1 and can thereby play a role in tumor suppression." (PMID 32087696, 2020). "In addition, Stat3 signaling controls MMP‐7 expression, which regulates tumor size and metastasis, in KrasG12D‐acinar cells." (PMID 32885589, 2020). "In tumor cells, HNK suppresses mitochondrial complex I-dependent respiration, stimulates the formation of mitochondrial ROS, induces AMPK activation, and inhibits mitochondrial STAT3 (signal transducer and activator of transcription) phosphorylation." (PMID 32264893, 2020). "The biology and biochemistry of JAKs, TYK2-dependent cytokines and cytokine signaling in tumor surveillance are well covered in recent reviews and the oncogenic properties of TYK2 are reviewed in the recent Special Issue ‘Targeting STAT3 and STAT5 in Cancer’ of Cancers." (PMID 31936322, 2020). "A promising strategy could be the inhibition of specific CSC-generating and CSC-expanding pathways, such as the Wnt, Shh, JAK/STAT3 and PI3/AKT signaling pathways, which regulate thyroid CSC self-renewal and tumor growth." (PMID 32796774, 2020). "Pleiotropic IL-9 can regulate the function of T cells, B cells, mast cells and airway epithelium cells by activating the STAT1, STAT3 and STAT5 signaling pathways, which are involved in the progression of tumor diseases, allergic diseases, inflammatory, and autoimmune diseases." (PMID 32228589, 2020). "The mTOR‐dependent regulation of STAT3 and NF‐κB activity promotes an immunosuppressed phenotype in TAM‐MG, which hinders effector T‐cell proliferation and immune reactivity and contributes to tumour immune evasion." (PMID 32567735, 2020). "Of note, TEXs induce the activation of Stat3 without promoting MDSC expansion while the tumor-derived soluble factors (TDSFs) trigger the expansion of MDSCs by activating the Erk signaling pathway." (PMID 32983146, 2020). "However, it inhibits EMT in OC cells by inhibiting the JAK/STAT3 and PI3K/Akt signaling pathways, resulting in the suppression of tumor volume in vivo by inhibiting tumor angiogenesis." (PMID 32509141, 2020). "The mechanism of how STAT3 regulates mitochondrial activity is not yet clear; however, specifically targeting mitochondrial activity is postulated to suppress tumor growth." (PMID 33003453, 2020). "Interestingly, EOC cells enriched from ascites showed constitutive phosphorylation of STAT1 and STAT3 and expression of IL-18BP and IDO1, suggestive of an in vivo role of STAT-activating cytokines in the EOC tumor environment." (PMID 32093058, 2020).
tumor (continued). "In NPC, Zhang and co-workers demonstrated that interlukin 6/ signal transducer and activator of transcription 3 (IL6/Stat3) signaling may enhance the growth and tumorigenicity of EBV-positive tumor cells via the upregulation of the EBV LMP-1 viral protein." (PMID 32752071, 2020). "In addition, external environmental agents can activate oncogenic STAT3/STAT5 signaling in malignant T cells leading to the release of IL-2 and other cytokines that eventually result in tumor progression." (PMID 33333886, 2020). "Indeed, TAMs have been proven to promote tumor cell migration and invasion by up-regulating COX-2 and MMP9 expression in osteosarcoma (OS) cells, promoting phosphorylation of STAT3 and inducing epithelial-mesenchymal transformation (EMT)." (PMID 33224886, 2020). "The Ser727 phosphorylation in STAT3 is positively related to tumor stage and size in estrogen receptor–negative breast cancer." (PMID 33003453, 2020). "Thus DDIAS sustains STAT3 phosphorylation by inhibiting the accessibility of PTPRM to STAT3, suggesting a novel mechanism of PTPRM as a tumor suppressor." (PMID 31900385, 2020). "Thus, our data indicate that increased tumorigenesis in Nod2−/− mice is associated with decreased activation of STAT3, ERK, and JNK during the early stages but increased activation of STAT3 and ERK during the later stages of tumor development." (PMID 33239685, 2020). "Moreover, they also confirmed that the down-regulation of LRRK2 in cultured tumor cells compromises MET activation and selectively reduces downstream MET signaling to mTOR and STAT3." (PMID 32196072, 2020). "Inhibition of STAT3 inhibits its target gene MMP2 and inhibits tumor cell invasion." (PMID 33330321, 2020). "Here, we investigated the interaction of SH2D4A and STAT3 to shed light on the non-canonical functions of STAT3 in cooperation with the tumor suppressor SH2D4A." (PMID 33257655, 2020). "This phenomenon increases the level of p-STAT3, resulting in the increased expression and secretion of MMP-9 and the formation of a positive feedback loop to maintain the invasion and metastasis of tumour cells." (PMID 32209138, 2020). "The relatively high expression of phosphorylated STAT3 has been observed in the tumor tissues compared to the non-diseased tumor surrounding tissues." (PMID 32967366, 2020). "Inhibiting STAT3 and NFAT pathway significantly suppressed gastric xenograft tumor growth." (PMID 32041943, 2020). "Our study demonstrated the ability of STAT3 decoy microbubbles and ultrasound to inhibit the growth of human HNSCC and downregulate target genes involved in signaling pathways that contribute to tumor cell survival and proliferation." (PMID 33206698, 2020). "The downregulation of tumor suppressors miR-124 and miR-214 mediates cSCC progression through induction of ERK kinases, while the reduced expression of miR-204 also targets MAPK cascade via STAT3." (PMID 32674318, 2020). "AMPK suppresses tumor survival through inhibition of mTOR by increasing the expression of p-TSC2, a tumor suppressor gene, and leads to the inactivation of AKT and lipopolysaccharide (LPS)-induced IL-6/JAK2/STAT3 signaling in triple-negative breast cancer (TNBC)." (PMID 31952344, 2020). "NHE-06 administration decreased IL-6 levels and downregulated IL-1β and COX-2 expression in mice bearing subcutaneous Hepa1-6 tumors, which is indicative of inactivated NF-κB/IL-6/STAT3 signaling and restored tumor immunity without direct tumor cytotoxicity." (PMID 32595757, 2020).
tumor (continued). "It has also been reported that STAT3 ablation reduced tumor growth, and the tumor cells did not progress to become more invasive than STAT3-expressing tumors." (PMID 33081347, 2020). "Functional interaction between CD44 and STAT3 can also occur at different levels of the TME, discussed in detail below, and encompass tumor endothelial cells, fibroblasts, and cells of the immune system, such as myeloid-derived suppressor cells, macrophages, and regulatory T and B cells." (PMID 33335857, 2020). "In B16STAT3β tumor-bearing mice, LPS had a less potent decreasing effect on the number of splenic CD8 T cells than in B16NC tumor-bearing mice, suggesting a role of STAT3 activation in LPS-induced splenic CD8 T cell reduction." (PMID 32312954, 2020). "STAT3 was also observed to be positively correlated with drug resistance towards DNR and 2-CdA in this data and has been described extensively as a regulator of pathways related to tumorigenesis, tumor growth, and drug resistance." (PMID 32429253, 2020). "Moreover, decreased expression of p-STAT3 and a concomitant downregulation of ERO1L were observed in tumor tissues derived from miR-144-3p-overexpressing CAL-27 cells compared to the corresponding control cells." (PMID 31942199, 2020). "By Day 12, the STAT3 decoy treated mice had a 2-fold reduction (p<0.05) in tumor volume compared to that of the no treatment control group and a 1.5-fold reduction (p<0.05) compared to that of STAT3-MB-mut + UTMC, respectively." (PMID 33206698, 2020). "Studies have shown that STAT3 is a transcription factor for the S1PR1 gene, and enhanced expression of S1PR1 can continuously activate STAT3 and upregulate the expression of the IL-6 gene, thereby accelerating tumor growth and metastasis." (PMID 33101013, 2020). "In conclusion, our research uncovered IL-37/STAT3/HIF-1α negative feedback signaling drives tumor development and Gem resistance in PDAC." (PMID 32226541, 2020). "Hyper-activated STAT3 regulates the expression of interferon γ (IFNγ), interleukin 12 (IL-12), CD86, C-C motif chemokine ligand 5 (CCL5), and C-X-C motif chemokine ligand 10 (CXCL10) in the tumor microenvironment to promote immune evasion." (PMID 32486001, 2020). "The analysis of the tumor inflammatory microenvironment composition in DLBCL patients revealed the significant increased number of CD163+ cells in the ABC group of patients and a positive correlation between CD163+ cells and STAT3 expression in tumor cells." (PMID 32731512, 2020). "One of the DAMPs, KRASG12D protein, is induced by oxidative stress from tumor cells and enveloped into exosomes then captured by macrophages through an AGER-dependent mechanism, which orchestrates M2 differentiation through STAT3-dependent fatty acid oxidation." (PMID 33505964, 2020). "To verify the role of IL-17A/STAT3 signaling on CD8+ T cell migration and tumor progression in vivo, we used immune-cell-infused xenograft mouse model according to previous studies, which may not represent tumor immunity." (PMID 32503584, 2020). "Among a variety of stimuli, TPA, as a tumor promoter, has been reported to induce MMP-9 expression by upregulating transcription factors, such as activator protein-1 (AP-1), signal transducer and activator of transcription-3 (STAT3), and nuclear factor kappa B (NF-κB)." (PMID 31893611, 2020). "Another study revealed that leptin provoked the JAK1/2, STAT3, FAK, ERK, and GSK3αβ signaling cascade to stimulate the production of soluble ICAM-1 in cancer cells, which induced osteoclast formation and enhanced tumor-induced osteolysis in vivo." (PMID 33371368, 2020). "ThesedsODN inhibit the stimulation of STAT-3 dimers; as a result, gene expressionactivated by STAT-3 and growth of tumor cells is inhibited.STAT-3-specific dsODN are also used in mouse to inhibit expression of STAT-3responsive genes and ultimately prevent tumor cell growth." (PMID 32167126, 2020).